SET (SET nuclear proto-oncogene)
Diseases named in the same sentence as SET in open-access papers (continued):
Sharing a sentence is not in itself a finding about the gene and the disease.
Cognitive impairment (5 papers, 2014 to 2024). Abnormal cognition is characterized by deficits in thinking, reasoning, or remembering. "Overexpression of CK2 in mouse hippocampus via virus injection induced cognitive deficit associated with SET Ser9 hyperphosphorylation." (PMID 29760653, 2018). "Cytoplasmic legumain is often associated with neurodegenerative phenotypes, where it cleaves tau, α-synuclein, and SET to promote neurofibrillary tangles, plaque formation, and cognitive impairment." (PMID 38199506, 2024). "Mutation in SET cause mental retardation, autosomal dominant 58 (OMIM: 618106), which is a rare hereditary neurological disease characterized by early-onset cognitive impairment." (PMID 33287870, 2020). "Together, these data strongly suggest that phosphorylation of SET at Ser9 is responsible for CK2 activation-induced cognitive defect through blocking PP2A phosphatase activity." (PMID 29760653, 2018). "To test whether SET phosphorylation by CK2 is really responsible for its overexpression-induced cognitive deficit, we firstly transfected HEK293/tau cells with WT SET or non-phosphorylation SET S9A in the presence of CK2." (PMID 29760653, 2018). "Together, our data demonstrate that CK2 phosphorylates SET at Ser9 leading to SET cytoplasmic translocation and inhibition of PP2A resulting in tau pathology and cognitive impairments." (PMID 29760653, 2018). "We found that non-phosphorylated SET reversed CK2 overexpression-induced pathology and cognitive defects." (PMID 29760653, 2018).
ovarian carcinoma (5 papers, 2016 to 2025). A malignant neoplasm originating from the surface ovarian epithelium. "SETBP1 has been identified as a key target of TRIM29, and the SETBP1/SET/PP2A axis has been shown to be essential for the progression of ovarian cancer driven by TRIM29." (PMID 39273321, 2024). "We noted a lower increase in SET gene expression induced by exosomes from ovarian cancer cells treated with α-mangostin and/or cisplatin." (PMID 36012171, 2022). "Additionally, VEZF1 activates SETBP1 transcription, and the SETBP1/SET/PP2A oncogenic signaling axis promotes the malignant phenotype of ovarian cancer cells." (PMID 40858565, 2025). "Furthermore, overexpression of tripartite motif-containing 29 (TRIM29) is closely associated with adverse clinical outcomes in ovarian cancer and promotes the proliferation, migration, and invasion of ovarian cancer cells via the SETBP1/SET/PP2A carcinogenic signal axis." (PMID 35898891, 2022). "Significant changes in gene expression in fibroblasts after treatment with exosomes from ovarian cancer cells were observed for HRAS and SET (SET nuclear oncogene)." (PMID 36012171, 2022). "Indeed, two novel anti-SET reagents, OP449 and FTY720, were found to promote cell death induced by cisplatin in ovarian cancer cell lines, again pointing to the significance of SET in cancer biology." (PMID 27775603, 2016).
acute leukemia (4 papers, 2019 to 2022). A clonal (malignant) hematopoietic disorder with an acute onset, affecting the bone marrow and the peripheral blood. "The interaction between SET and KMT2A, a gene that is frequently rearranged in acute leukemias, might suggest a role for SET in KMT2A-mediated transcription and possibly chromatin maintenance." (PMID 36345878, 2022). "Chromosomal translocations fusing the locus of nucleoporin NUP214 each with the proto-oncogenes SET and DEK are recurrent in, largely intractable, acute leukemias." (PMID 32934780, 2020). "Chromosomal translocations involving the NUP214 locus are recurrent in acute leukemia and frequently fuse the C-terminal region of NUP214 with SET and DEK, two chromatin remodeling proteins with roles in transcription regulation." (PMID 30669574, 2019).
Intellectual disability (4 papers, 2019 to 2025). "SET variants were linked to moderate intellectual disability and in most cases speech delays were reported." (PMID 39580495, 2024).
metastatic colorectal cancer (4 papers, 2018 to 2020). "The tumor suppressor microRNA (miR)-199b directly targets the PP2A inhibitor SET, which has been involved in 5-FU resistance, and its downregulation has been found to correlate with poor outcome in metastatic colorectal cancer." (PMID 32580513, 2020). "SET nuclear proto-oncogene (SET) deregulation is a novel molecular target in metastatic colorectal cancer (CRC)." (PMID 30871013, 2019).
metastatic disease (4 papers, 2015 to 2024). "More importantly, both ZBTB11 and SET showed a further increase in their expression in metastatic tumors, strongly supporting critical roles of aberrant ZBTB11 and SET in modulating distal metastasis of lung tumors." (PMID 38355937, 2024). "Levels of PP2A phosphorylation together with SET and CIP2A protein expression were studied in 24 PCa patients and both were associated with high Gleason scores and presence of metastatic disease." (PMID 26023836, 2015). "Moreover, our group recently reported that miR-199b downregulation was significantly associated with SET overexpression in a set of 29 CRC patients without metastatic disease." (PMID 32580513, 2020). "To determine its clinical relevance, we quantified SET in a series of 231 CRC patients without metastatic disease at diagnosis, observing that SET overexpression is a common alteration that is associated with relapse and predicts shorter overall survival and time to metastasis." (PMID 30871013, 2019). "In addition, we evaluated the protein levels of ZBTB11 and SET in tissue arrays containing paired adjacent normal lung tissues and primary LUAD and distal metastatic tumors." (PMID 38355937, 2024). "To study the prevalence and clinical significance of SET overexpression, we quantified the expression of SET by immunohistochemistry in a cohort of 247 CRC patients without metastatic disease at diagnosis." (PMID 30871013, 2019). "To further investigate the significance of SET deregulation in CRC, we evaluated its expression in earlier stages of CRC, studying a cohort of 231 CRC patients without metastatic disease." (PMID 30871013, 2019).
polycystic ovaries (4 papers, 2013 to 2018). "The different expression of SET protein in polycystic ovaries and normal ovaries was detected by Western blot." (PMID 23861679, 2013). "Our previous study showed that SET protein was differently expressed in polycystic ovaries by microarray assay." (PMID 23861679, 2013). "Expression of SET protein in polycystic ovaries was triple times higher than that in normal ovaries (P < 0.05)." (PMID 23861679, 2013). "In the present study, we firstly investigated the cellular localization of SET protein in human ovaries and its different expression in the polycystic ovaries compared with human normal ovaries of adult women." (PMID 23861679, 2013). "The level of SET protein expression in polycystic ovaries was triple higher than that in normal ovaries (P < 0.05)." (PMID 23861679, 2013). "And expression of SET protein in polycystic ovaries was found to be triple times higher than that in normal ovaries by Western blotting." (PMID 23861679, 2013). "Our previous studies have also found that SET was one of the overexpressed genes in polycystic ovaries compared to normal ovaries using cDNA microarray technology." (PMID 23421880, 2013). "We found previously that the expression of SET gene was up-regulated in polycystic ovaries." (PMID 23421880, 2013).
chronic lymphocytic leukemia (3 papers, 2015 to 2019). "The oncoprotein SET is a potent inhibitor of the PP2A holoenzyme, whose levels are dramatically increased in primary chronic lymphocytic leukemia (CLL) and non-Hodgkin lymphoma (NHL) cells." (PMID 31225502, 2019).
glioblastoma (3 papers, 2021 to 2022). The most malignant astrocytic tumor (WHO grade IV). "As SET was downregulated in both U-87 MG and SH-SY5Y cells, MS13 may also induce its anti-cancer effects in both glioblastoma and neuroblastoma by serving as a SET inhibitor." (PMID 33996900, 2021). "It has been shown that in more than 50% (59.6%) of glioblastoma cases, the activity of PP2A is inactivated or dysregulated due to overexpression of its inhibitors, especially SET and CIP2A." (PMID 36555359, 2022).
lung adenocarcinoma (3 papers, 2013 to 2023). A carcinoma that arises from the lung and is characterized by the presence of malignant glandular epithelial cells. "The significance of I2PP2A/SET in lung tumours was further explored by IHC using a tumour micro-array (TMA) containing lung adenocarcinoma (n = 48), adjacent lung (n = 48) and normal lung tissues (n = 4)." (PMID 23180565, 2013). "It promotes the progression of lung adenocarcinoma by targeting the SET/TAF-Iα fraction." (PMID 36688087, 2023). "To examine if P-FTY720 is involved in targeting I2PP2A/SET leading to tumour growth inhibition in vivo, we implanted Lewis lung adenocarcinoma cell (LLC)-derived allografts in the flanks of SK-2−/− compared to WT mice and treated with oral doses of 10 mg/kg FTY720." (PMID 23180565, 2013).
acute promyelocytic leukemia (2 papers, 2014 to 2021). An aggressive form of acute myeloid leukemia (AML), characterized by arrest of leukocyte differentiation at the promyelocyte stage, due to a specific chromosomal translocation t(15;17) in myeloid cells. "We also demonstrated that the knockdown of SET gene resulted in the upregulation of protein phosphatase 2 (PP2A) expression and the downregulation of promyelocytic leukemia and retinoic acid receptor α fusion gene (PML-RARα) expression, which were enhanced by As4S4 treatments." (PMID 24454695, 2014). "ERK inhibition or heterogeneous nuclear ribonucleoprotein K knockdown decreases cell viability, increases all‐trans retinoic acid (ATRA)‐induced differentiation in acute promyelocytic leukemia (APL) ATRA‐resistant cells, and promotes SET cleavage." (PMID 34058077, 2021).
brain ischemia (2 papers, 2019 to 2024). Diminished or absent blood supply to the brain caused by obstruction (thrombosis or embolism) of an artery resulting in neurologic damage. "Under acidic conditions (e.g., brain ischemia, hypoxia, or AD), legumain can translocate from neuronal lysosomes into the cytoplasm, where it cleaves I2PP2A (also known as SET)." (PMID 31607898, 2019). "AEP has been reported to specifically cleave SET, an inhibitor of DNase, and thus induces DNA damage during seizures and cerebral ischemia, which may represent a possible mechanism by which AEP regulates RIBI." (PMID 38655198, 2024).
cervical cancer (2 papers, 2014 to 2016). A primary or metastatic malignant neoplasm involving the cervix. "It would be of interest to determine whether Grp58 regulates apoptosis through the SET complex and associated proteins that participate in cervical cancer progression and drug resistance." (PMID 25081282, 2014). "There is also data indicating that, in cervical cancer HeLa cells, forced SET overexpression and manipulation of SET cytoplasmic localization affected cell motility, implicating SET involvement in cancer metastasis." (PMID 27775603, 2016).
choriocarcinoma (2 papers, 2019 to 2020). An aggressive malignant tumor arising from trophoblastic cells. "MiR-199b has been shown to directly target SET Nuclear Proto-Oncogene (SET) in choriocarcinoma, and our group demonstrated that SET is also a direct target of this miR in CRC." (PMID 32731550, 2020).
colorectal adenocarcinoma (2 papers, 2014). The most common type of colorectal carcinoma. "Although, it was shown that the SET expression level was markedly increased following silencing of the FBXL20 gene in the colorectal adenocarcinoma cell lines, SW480 and SW620." (PMID 24932313, 2014). "In addition, the E-cadherin and SET expression levels were markedly upregulated when the FBXL20 gene was knocked out in colorectal adenocarcinoma." (PMID 24932313, 2014). "SET is overexpressed and has been found to play a role in acute myeloid leukemia oral carcinoma and ovarian cancer, but its involvement in the development of colorectal adenocarcinoma remains unknown." (PMID 24944693, 2014). "In the present study, the mRNA expression levels of SET, PP2A and β-catenin were examined in 31 pairs of human colorectal adenocarcinoma tissues and corresponding adjacent normal colorectal tissues by quantitative real-time polymerase chain reaction (qPCR)." (PMID 24944693, 2014).
endometrial carcinoma (2 papers, 2021 to 2022). A malignant tumor arising from the epithelium that lines the cavity of the uterine body. "In addition, we show that human endometrial carcinomas with PPP2R1A, SET and CIP2A mutations or changes in mRNA levels are associated with higher mutation burden and MSI status." (PMID 34911954, 2021).
gonadoblastoma (2 papers, 2011 to 2014). A mixed germ cell/sex cord-stromal tumor characterized by the presence of large germ cells which resemble seminoma cells and small cells which resemble Sertoli or granulosa cells. "TSPY1 is a member of the TSPY/SET/NAP1 superfamily mapped to the critical region harboring the gonadoblastoma locus which was the only oncogenic on the male-specific Y chromosome (GBY)." (PMID 24586606, 2014).
hyperandrogenism (2 papers, 2013 to 2018). Excessive secretion of androgens from the adrenal glands or gonads. "Additional studies are required to examine whether and how SET overexpression in theca cells contributes to hyperandrogenism of PCOS." (PMID 23861679, 2013). "The increased expression of SET protein in polycystic ovarian tissues may be partly a potential mechanism in the pathophysiology of hyperandrogenism in PCOS." (PMID 23861679, 2013).
invasive breast carcinoma (2 papers, 2021 to 2023). A carcinoma that infiltrates the breast parenchyma. "SET is a nuclear protein, hence strong overexpression of SET was detected in the nuclei of invasive breast carcinoma tissue." (PMID 37097392, 2023). "SET, an endogenous inhibitor of protein phosphatase 2A, was overexpressed in all subtypes of invasive breast carcinoma tissues." (PMID 34244560, 2021). "SET protein is a nuclear protein, and hence strong expression of SET was detected in the nuclei of invasive breast carcinoma tissues." (PMID 34244560, 2021).
medulloblastoma (2 papers, 2018 to 2021). A malignant, invasive embryonal neoplasm arising from the cerebellum. "Besides the pharmacological inhibition of SET, other studies have shown that knocking down SET in Smo1 primary medulloblastoma cells induces cell death, suggesting a potential function of the oncoprotein in Hh signaling." (PMID 34230583, 2021). "In the current study, we demonstrated that PP2A and its two endogenous inhibitors I2PP2A/SET and CIP2A are expressed in medulloblastoma PDX cells." (PMID 29720672, 2018). "In addition, FTY720 treatment of human medulloblastoma PDXs resulted in activation of PP2A in the face of decreased overall PP2A protein expression, but changes in I2PP2A/SET or CIP2A expression were not consistently seen." (PMID 29720672, 2018).
myeloproliferative diseases (2 papers, 2012 to 2023). "It is also important to note that Hsp90, SET, RPSA have all been implicated in myeloproliferative neoplasms." (PMID 22723854, 2012). "Hsp90 is a therapeutic target in JAK2-dependent myeloproliferative neoplasms, RPSA is highly expressed in Acute Myeloid Leukaemia (AML) and SET expression is induced in Chronic Myelogenous Leukemia (CML)." (PMID 22723854, 2012).
non-Hodgkin lymphoma (2 papers, 2016 to 2019). Distinct from Hodgkin lymphoma both morphologically and biologically, non-Hodgkin lymphoma (NHL) is characterized by the absence of Reed-Sternberg cells, can occur at any age, and usually presents as a localized or generalized lymphadenopathy associated with fever and weight loss. "Therefore, in this work, we focused on SET and sought to determine the role of the SET/PP2A axis in T-ALL by using a SET antagonist, OP449, which has been previously shown to be effective against CLL, non-Hodgkin's lymphoma, CML, and AML cells ex vivo." (PMID 27705940, 2016).
viral infection (2 papers, 2015 to 2022). "Simultaneous mutation of three key residues in the SET interaction domain led to a complete loss of SETD3′s ability to support viral infection, even when this mutant (SET257+266+288) was overexpressed to levels much higher than endogenous SETD3." (PMID 36075902, 2022). "Upon transfection or viral infection of the SET-RW construct to 293T cells the SET-HA fusion is clearly seen migrating slightly above the endogenous SET band (lanes 2, 3) with HA expression only observed in cells containing exogenous SET-HA." (PMID 26563471, 2015). "Altogether these data indicate that the SET interface is critical for SETD3 binding to 2A, thus supporting viral infection." (PMID 36075902, 2022). "Strikingly, the combination of three mutations in the SET interface (SET257+266+288) that led to a complete loss of binding, failed to restore viral infection." (PMID 36075902, 2022).
autism (1 paper, 2020). Persistent deficits in social interaction and communication and interaction as well as a markedly restricted repertoire of activity and interest as well as repetitive patterns of behavior. "The gene encoding the protein SET, which showed increased expression level in the cortical synapse in female mice, is listed as strong ASD candidate (category 2) in the SFARI autism gene database." (PMID 32012899, 2020).
brain tumors (1 paper, 2025). "PRDM13, a neuron-specific PR/SET protein, regulates GABAergic vs. glutamatergic fate during cerebellar development and is frequently silenced by promoter methylation in embryonal brain tumors." (PMID 41228218, 2025).
chronic leukemia (1 paper, 2019). A slowly progressing leukemia characterized by a clonal (malignant) proliferation of maturing and mature myeloid cells or mature lymphocytes. "Moreover, SET expression was observed in the lymphocyte lineage, such as acute/chronic leukemia cells and natural killer cells." (PMID 31557212, 2019).
Down syndrome (1 paper, 2014). "More recently, we also observed an increase of SET associated with its cytoplasmic translocation in the hippocampus of Down syndrome patients and in the CA1 of AD patients." (PMID 24981783, 2014).
gallbladder cancer (1 paper, 2020). "For example, lncRNA-HGBC regulates gallbladder cancer progression by interacting with miR-502-3p, thus sequestering miR-502-3p and downregulating SET expression." (PMID 33121524, 2020).
hyperplasia (1 paper, 2015). An abnormal increase in the number of cells in an organ or a tissue with consequent enlargement. "Using prostate regeneration assays, we show that in vivo SET overexpression is sufficient to induce hyperplasia and prostatic intraepithelial neoplasia." (PMID 26563471, 2015).
invasive carcinoma (1 paper, 2021). A carcinoma that is not confined to the epithelium, and has spread to the surrounding stroma. "Immunohistochemical staining of breast tissue array containing 24 cases each of normal tissue, adjacent normal tissue, and invasive ductal carcinoma revealed that the SET protein was significantly overexpressed in invasive carcinoma tissues compared to normal and adjacent normal tissues." (PMID 34244560, 2021). "Thus, the SET protein was overexpressed in invasive carcinoma irrespective of hormone receptor expression status." (PMID 34244560, 2021).
kidney cancer (1 paper, 2016). Primary or metastatic malignant neoplasm involving the kidney. "Interestingly, SET expression is deregulated in more than 10 % of kidney cancer samples, a cancer type where we have previously demonstrated increased nuclear translocation of galectin-3." (PMID 27435226, 2016).